ZBP1 (Z-DNA binding protein 1)
Diseases named in the same sentence as ZBP1 in open-access papers (continued):
Sharing a sentence is not in itself a finding about the gene and the disease.
melanoma (continued). "Depletion of ZBP1 markedly decrease PANoptotic cell death in adrenocortical carcinoma, breast cancer and head and neck squamous cell carcinoma cells, and results in a significant tumorigenesis in colorectal cancer, melanoma and hemophagocytic lymphohistiocytosis mice models." (PMID 40721869, 2025). "In malignant melanoma and CRC, RIPK3 can interact with ZBP1 through RHIM, driving the recruitment of caspase-6 and caspase-8 to form the ZBP1–PANoptosome complex, which activates the NLRP3 inflammasome and induces PANoptosis." (PMID 38684668, 2024). "Another study showed that ZBP1 expression was significantly increased in mouse colon adenocarcinoma MC38 cells and mouse melanoma B16-SIY cells after radiation treatment, which subsequently activated MLKL to induce tumor cell necroptosis." (PMID 37771585, 2023). "In mouse melanoma B16-F10 and YUMMER1.7 tumor models, the combined administration of CBL0137 and PD-1 antibodies significantly reduced tumor volume in a ZBP1-dependent manner." (PMID 37771585, 2023). "In a previous study using murine colorectal cancer and melanoma models, ADAR1 was found to suppress ZBP1-mediated inflammasome activation and PCD, including apoptosis, necroptosis, and pyroptosis." (PMID 36845119, 2023). "We found that ZBP1 knockdown leads to the reduction of tumor necrosis and MLKL phosphorylation, but increases of cleaved Casp-3 and TUNEL positive cells in B16 melanoma tumors." (PMID 33976222, 2021). "Although higher transfection efficiency was obtained in WEHI 164 cells, similar sensors (DAI/ZBP1, DDX60 and p204) were upregulated in two cell lines TS/A and WEHI 164 as in our previous study on B16F10 melanoma cells." (PMID 29721152, 2018). "The upregulation of DAI/ZBP1, DDX60, and p204 was detected previously in B16.F10 melanoma cells, and this was confirmed in TS/A mammary carcinoma cells." (PMID 29721152, 2018). "To date, Z‐DNA binding protein 1 (ZBP1)‐, Absent in Melanoma (AIM)‐, receptor‐interacting serine/threonine‐protein kinase 1 (RIPK1)‐, and NLR family pyrin domain containing 12 (NLRP12)‐ PANoptosomes have been characterized at the molecular level." (PMID 41362050, 2026). "dsDNA also activates other inflammasomes containing AIM2 (absent in melanoma 2) and ZBP1 (Z-DNA binding protein 1)." (PMID 41596316, 2026). "To date, four distinct PANoptosomes have been identified: Z-DNA-binding protein 1 (ZBP1), absent in melanoma 2 (AIM2), receptor-interacting protein kinase 1 (RIPK1), and nucleotide-binding leucine-rich repeat-containing receptor 12 (NLRP12) PANoptosomes." (PMID 40568592, 2025). "Additionally, in B16 melanoma models, combined IFN-γ and KPT-330 treatment induced ZBP1-dependent PANoptosis, effectively inhibiting tumor progression." (PMID 41430036, 2025). "The increased expression of ZBP1 and RIPK3 also happens in mouse melanoma B16, mouse lung cancer LLC, human breast cancer MCF-7 and MDA-MB-231 tumors as their expression levels are significantly higher in the cells from tumors compared to that in the cultured parental cells." (PMID 33976222, 2021). "Free exogenous viral DNA in the cytosol is recognized by either Z-DNA binding protein 1 (ZBP1), absent in melanoma 2 (AIM2), or cGAMP synthase (cGAS)." (PMID 27379086, 2016). "Moreover, the CDK1 inhibitor CurE induces ZBP1-dependent PANoptosis and suppresses the proliferation of adrenocortical carcinoma cells, and adenosine deaminase acting on RNA 1 (ADAR1) depletion exerts similar effects under the treatment of NEIs plus IFN-γ in colorectal cancer and melanoma models." (PMID 40721869, 2025). "Apart from cGAS, a DNA sensor located in the cytoplasm, Z-DNA binding protein 1 (ZBP1) and absent in melanoma 2 (AIM2) also serve as sensors for cytosolic DNA." (PMID 41226461, 2025). "This complete lack of the ZBP1 Z-RNA sensor may be relevant to the unexpected PKR activation in A172 cells, in contrast to no PKR activation in Yumm1.7 melanoma cells." (PMID 41608661, 2026).
melanoma (continued). "The major nucleic acid sensors involved in DNA recognition are TLR9, cyclic GMP-AMP synthase (cGAS)-stimulator of interferon genes (STING), absent in melanoma 2 (AIM2) and Z-DNA-binding protein 1 (ZBP1), with the three latter ones being cytoplasmic DNA sensing mechanisms." (PMID 39090111, 2024).
breast cancer (25 papers, 2013 to 2025). A primary or metastatic malignant neoplasm involving the breast. "Importantly, ZBP1 deficiency prevents tumor necrosis and inhibits metastasis during breast cancer progression." (PMID 37061535, 2023). "The COF-based PorSe-CuPt@CBL, preloaded with ZBP1 agonist CBL0137 under radiotherapy treatment, generates substantial amounts of ROS, which effectively trigger ZBP1-mediated PANoptosis and potentiate breast cancer treatment." (PMID 40721869, 2025). "Different from other tumors in which necroptosis is triggered through the typical RIPK1-RIPK3-MLKL pathway, breast cancer (BC) uniquely depends on ZBP1 as the central regulator of this process." (PMID 41267084, 2025). "Deletion of ZBP1 blocked tumor necroptosis during tumor development and inhibited breast cancer metastasis, suggesting that ZBP1 is the key regulator of tumor necroptosis and provides a potential therapeutic target for controlling tumor metastasis." (PMID 38684755, 2024). "In human cancers like gastric cancers and breast cancers, ZBP1 expression is increased, which also correlates with poor prognoses." (PMID 37089261, 2023). "Nutrient deprivation (glucose or serum) induces ZBP1-mediated necroptosis of breast cancer cells, suggesting ZBP1 expression is increased during starvation." (PMID 37759572, 2023). "For example, downregulation of the RNA-binding protein ZBP1 in metastatic breast cancer cells increased cell migration by altering the expression of mRNAs involved in cell-cell adhesion, cytoskeleton, and cell proliferation." (PMID 34141606, 2021). "ZBP1 stabilizes intercellular connections and focal adhesions, which suppresses breast cancer cell invasion." (PMID 34867395, 2021). "Through bioinformatic analysis of the human cancer datasets, we found that human ZBP1 expression is significantly increased in human breast cancer and several other types of solid tumors when compared to their normal tissue." (PMID 33976222, 2021). "Invasive carcinoma cells derived from primary mammary tumors have reduced levels of an RNA binding protein IMP1/ZBP1/IGF2BP1, required for β-actin mRNA localization." (PMID 27655671, 2016). "In human breast cancer cells, repression of ZBP1 leads to increased cell proliferation and migration." (PMID 24622399, 2014). "To address this in further detail, we transduced breast cancer-derived MCF7 cells, which express IGF2BP1 at barely detectable levels, with lentiviral vectors encoding either GFP or GFP-fused ZBP1, the chicken ortholog of IGF2BP1." (PMID 23677615, 2013). "In breast cancer, glucose restriction induces ZBP1‐dependent necroptosis." (PMID 41299204, 2025). "ZBP1 plays crucial biological roles in various types of cancer, such as breast cancer and myeloma." (PMID 40148674, 2025). "In agreement, increased ZBP1 expression correlated with breast cancer aggressiveness." (PMID 37759572, 2023). "In breast cancer cells glucose deprivation triggers ZBP1-depedent necroptosis." (PMID 36186456, 2022). "In a breast cancer study, ZBP1 expression is dramatically upregulated in necrotic tumors." (PMID 35610275, 2022). "However, the mRNAs of TLR3, Ifih1/MDA5, Zbp1, Ddx60 and Ifi204 were upregulated by varying degrees after poly(I:C) transfection in both mammary carcinoma and fibrosarcoma cells." (PMID 35737804, 2022). "Previous studies have shown that ZBP1 is able to mediate directional motility of cells and to repress the invasion of breast cancer cells through regulating the localized expression of many adhesion- and motility-related mRNAs, including β-actin, Arp-16 and α-actinin mRNAs." (PMID 25588836, 2015). "Moreover, although ZBP1 is highly expressed in advanced, necrotic tumors and triggers necroptosis of tumor cells, ZBP1-dependent necroptosis was found to facilitate metastasis in breast cancer models." (PMID 37450010, 2023).
breast cancer (continued). "ZBP1 was shown to bind to and stabilize β-catenin, P16-ARC and E-cadherin mRNAs in metastatic breast cancer cells, suggesting a role of CRD-BP in strengthening cell-cell contacts and thus inhibiting tumour-cell invasion." (PMID 24622399, 2014). "Here the authors show that ZBP1 is an upstream mediator of RIPK3 in tumour necroptosis and that glucose deprivation induces the release of mitochondrial DNA, which binds to ZBP1 to activate ZBP1-mediated necroptosis in breast cancer." (PMID 33976222, 2021). "Importantly, we demonstrated that deletion of ZBP1 blocks necroptosis of tumor cells during tumor development and consequently inhibits tumor metastasis in MVT-1 breast cancer model." (PMID 33976222, 2021).
influenza (23 papers, 2011 to 2025). An acute viral infection of the respiratory tract, occurring in isolated cases, in epidemics, or in pandemics; it is caused by serologically different strains of viruses (influenzaviruses) designated A, B, and C, has a 3-day incubation period, and usually lasts for 3 to 10 days. "The role of ZBP1 isoforms in human susceptibility to severe influenza remains unexplored, offering a precision medicine avenue." (PMID 40943452, 2025). "Through Gene AnalyticsTM, ZBP1 was found to be differentially expressed in blood, further supporting its association with influenza." (PMID 39874350, 2025). "Of note, only mutation of the Zα2 domain was necessary to eliminate ZBP1 activation following influenza infection indicated different requirements for influenza and herpes viruses." (PMID 30050136, 2018). "Infection studies using highly pathogenic influenza strains (H5N1 or H7N9) may facilitate the identification of the role of ZBP1 in host defense or disease pathogenesis." (PMID 35587190, 2022). "The role of ZBP1 in viral infections, such as influenza and cytomegalovirus, has been well investigated." (PMID 40006996, 2025). "ZBP1 initiates cell death signaling pathways during influenza infection by recognizing viral Z-RNAs." (PMID 39591329, 2024). "A recent study demonstrates the formation of influenza Z-RNAs and their localization with ZBP1 in the nucleus, providing substantial evidence of Z-RNA formation in infected cells and its sensing by ZBP1." (PMID 35587190, 2022). "Although moderate ZBP1 activation mediates host defense against certain pathogens, excessive and prolonged ZBP1 activation has been documented to paradoxically exacerbate chronic inflammation and influenza pathogenesis." (PMID 36539813, 2022). "ZBP1 is primarily a cytoplasmic protein that translocates to the nucleus and colocalizes with influenza Z-RNAs following infection." (PMID 35587190, 2022). "Although nuclear translocation of ZBP1 is crucial for influenza-induced cell death, restricting its localization only to the cytoplasm does not inhibit cell death responses during IAV infection." (PMID 35587190, 2022). "Loss of ZBP1 expression confers high susceptibility, poor control of viral spread, and reduced survival rates after IAV infection in mice, suggesting the protective role of ZBP1 in influenza infection." (PMID 35587190, 2022). "Recent studies demonstrate an unexpected role of ZBP1 in sensing influenza infection to trigger multimodal PCD and proinflammatory cytokine release." (PMID 35587190, 2022). "Among these was ZBP1, a sensor of influenza infection that triggers cell death and inflammation and contributes to virus-induced lethality." (PMID 30446528, 2018). "MCMV-induced necroptosis requires viral transcription, and, recently, evidence with influenza suggested that viral RNP complexes promote ZBP1 activation." (PMID 30050136, 2018). "Furthermore, ZBP1 is involved in other viral respiratory diseases such as influenza, MERS-CoV, and SARS-CoV." (PMID 38714196, 2024). "Additionally, caspase-6 has been shown to enhance necroptosis during influenza infection by promoting the RHIM-dependent interaction between ZBP1 and RIPK3, thereby facilitating both necroptosis and apoptosis." (PMID 39591329, 2024). "The emergence of ZBP1 in sensing influenza infection spurred its function in viral RNA sensing." (PMID 35587190, 2022). "RHIM-function of ZBP1 in influenza induced cell death and inflammation." (PMID 35587190, 2022). "In the context of influenza infection, the innate immune sensor ZBP1 is emerging as a key regulator of the concurrent induction of NLRP3-dependent pyroptosis, mixed-lineage kinase domain-like pseudokinase (MLKL)-dependent necroptosis, and CASP8-dependent apoptosis." (PMID 32152420, 2020). "Influenza, a respiratory illness like SARS-CoV-1 and -2, was expected to lead to differential expression of BST2, IFITM1, and ZBP1." (PMID 39874350, 2025).
influenza (continued). "A separate group found that BST2 is involved in suppressing SARS-CoV-2 replication in vitro, and ZBP1 can decrease the replication of SARS-CoV-1, SARS-CoV-2, influenza, and other viruses." (PMID 39874350, 2025). "In recent years, studies have shown that ZBP1 is a key mediator of PANoptosis and drives NLRP3-inflammasome activation during an influenza infection, which subsequently mediates cytokine release." (PMID 40006996, 2025). "In ZBP1-PANoptosome, ZBP1 acts as a PANoptosis senor to activate NLRP3 inflammasome, caspase-8, RIPK1, and RIPK3 in response to influenza A virus (IAV) infection." (PMID 39465258, 2024). "Of note, ZBP1 is capable of triggering pyroptotic cell death via activating NLRP3 inflammasome, which further aggravate the seriousness of influenza infection." (PMID 34643045, 2021). "Following influenza infection, the RIG-I pathway drives IFN production that in turn elevates ZBP1 to levels sufficient to support necroptosis." (PMID 30050136, 2018). "Their influenza classifier genes showed mostly IFN regulated genes, several of which (Ifi44, G1p2, Oas1, Zbp1) showed overlap with our signature." (PMID 21731757, 2011). "In influenza-infected alveolar epithelial type I (LET1) cells, ZBP1 is capable of activating RIPK1." (PMID 39591329, 2024). "Moreover, Z-DNA-binding protein 1 (ZBP1), a novel effector of necroptosis, triggers NLRP3 inflammasome activation and release of IL-1β through the RIPK1-RIPK3-Caspase-8 axis during influenza A virus (IAV) infection." (PMID 36619743, 2022). "A recent study showed that influenza H1N1(A/Puerto Rico/8/34, PR8/H1N1) induces necroptosis in murine fibroblast through the detection of viral RNA with the intracellular immune sensor, Z-DNA-binding protein 1 (ZBP1), and subsequent activation of RIPK32." (PMID 31165725, 2019).
COVID-19 (18 papers, 2021 to 2025). A disease caused by infection with severe acute respiratory syndrome coronavirus 2. "In COVID-19 patients, ZBP1 expression was increased in immune cells from those who succumbed to the disease." (PMID 40416961, 2025). "There is evidence that ZBP1 is involved in the induction of inflammatory responses in COVID-19 patients." (PMID 38714196, 2024). "In this regard, there is evidence that the ZBP1 signaling pathway worsens the condition of COVID-19 patients by damaging lung epithelial cells." (PMID 38714196, 2024). "In addition, increased expression of MDA5 in females may be due to stronger and more appropriate immune responses against SARS-CoV-2, and elevated expression of AIM2 and ZBP1 genes might be associated with the more severe manifestation of COVID-19 in male patients." (PMID 38714196, 2024). "Elevated levels of ZBP1 correlate with poor outcomes in COVID-19 patients, where ZBP1-induced PANoptosis and the resultant cytokine storm hinder effective treatment." (PMID 39591329, 2024). "The ZBP1 transcript was significantly different between PBMCs and nasopharyngeal epithelial cells of all COVID-19 patients compared with the healthy group." (PMID 38714196, 2024). "We also observed that severe COVID-19 patients treated with dexamethasone had decreased ZBP1 expression." (PMID 37033961, 2023). "The results revealed that the expression level of ZBP1 gene in COVID-19 patients significantly increased compared to the control group." (PMID 36320810, 2022). "Together, these data suggest a positive correlation between ZBP1 expression and lethality in patients with COVID-19." (PMID 35587515, 2022). "Overall, our results suggest that IFN-based treatments for COVID-19 face therapeutic challenges due to ZBP1-mediated inflammatory cell death that contributes to cytokine storm, tissue damage and ultimately lethality." (PMID 35587515, 2022). "In patients with COVID-19, expression of the innate immune sensor ZBP1 was increased in immune cells from those who succumbed to the disease compared with those who recovered, further suggesting a link between ZBP1 and pathology." (PMID 35587515, 2022). "Moreover, ZBP1 mRNA was significantly elevated in the nasopharyngeal epithelial cells compared with the PBMC samples of COVID-19 patients with mild disease (P = 0.0008)." (PMID 38714196, 2024). "We can thus speculate that reduction in ZBP1 by dexamethasone may similarly limit the inflammatory cell death in severe COVID-19 and may facilitate an improved therapeutic response." (PMID 37033961, 2023). "In addition, increased levels of ZBP1 were found in patients who succumbed to COVID-19 compared with those who recovered." (PMID 38129399, 2023). "However, we observed that critically ill patients with COVID-19 showed increased IFN responses and ZBP1 expression compared to non-critical patients with COVID-19, suggesting that IFNs and ZBP1 are associated with the disease progression and mortality." (PMID 35587515, 2022). "Whether ZBP1 has a role in driving the pathology during severe COVID-19 or whether it has an impact on the efficacy of IFN-based therapies is not known." (PMID 35587515, 2022). "Importantly, elevated expression of ZBP1 has been reported in patients suffering from severe COVID-19, thereby suggesting that it might be involved in the pathogenesis of SARS-CoV-2." (PMID 39874350, 2025). "Interestingly, single cell transcriptomic studies recently showed that the expression of ZBP1 was increased in immune cell subsets from patients with COVID-19 as compared to healthy controls, and this increased expression correlated with increased patient mortality." (PMID 37033961, 2023). "Moreover, ZBP1-induced PANoptosis and cytokine storms impair the treatment of COVID-19." (PMID 38129399, 2023). "Therefore, we hypothesized that ZBP1 may be involved in lethality observed in patients with severe COVID-19." (PMID 35587515, 2022).